GLI1 (GLI family zinc finger 1)
Diseases named in the same sentence as GLI1 in open-access papers (continued):
Sharing a sentence is not in itself a finding about the gene and the disease.
chondrosarcoma (9 papers, 2014 to 2024). A malignant cartilaginous matrix-producing mesenchymal neoplasm arising from the bone and soft tissue. "Our analysis identified 26 GLI1low and 33 GLI1high chondrosarcoma samples, which correlated with tumor grade and suggests that GLI1 expression promotes chondrosarcoma progression." (PMID 37488121, 2023). "As the Hedgehog-GLI1 signal pathway is activated in chondrosarcoma, we established a vivo subcutaneous xenograft model by SW1353 cells." (PMID 37488121, 2023). "To further determine the mechanism of the Hedgehog-GLI1 signal in malignant chondrosarcoma, we reanalyzed a gene expression profiling of 17 fresh frozen chondrosarcoma biopsies." (PMID 37488121, 2023). "According to our previous research and the public data, we found that the Hedgehog-GLI1 signal pathway is aberrantly activated in chondrosarcoma." (PMID 37488121, 2023). "According to the results, we deeply deem that Hedgehog-GLI1 pathway is on state and further activates the downstream signals in chondrosarcoma." (PMID 37488121, 2023). "We also validated these results using qRT-PCR to assess the level of GLI1 expression in our collected chondrosarcoma samples (excluding dedifferentiated chondrosarcoma to match the public microarray data)." (PMID 37488121, 2023). "In conclusion, our results indicated that the Hedgehog-Gli1 signal pathway was activated in chondrosarcoma, which further enhanced the RNAP III signal pathway to mediate endogenous tRNA fragments synthesis." (PMID 37488121, 2023). "In parallel with the activated hedgehog signal pathway, our study highlighted that RNAP III transcription is more frequent in the GLI1 high-expression population in chondrosarcoma." (PMID 37488121, 2023). "In this study, we indicated that the Hedgehog-GLI1 signal pathway is activated in chondrosarcoma, which further enhances the RNAP III signal pathway to mediate endogenous tRNA fragments synthesis." (PMID 37488121, 2023). "Perturbation of the hedgehog pathway and overexpression of GLI1, a downstream transcription factor in the hedgehog pathway, are highly relevant to several malignancies including chondrosarcoma (CS)." (PMID 33637972, 2021). "GLI1 inhibition has been reported to repress cell growth and cell cycle progression and promote apoptosis in human chondrosarcoma cells." (PMID 32206038, 2020). "To elucidate potential underlying mechanisms, we identified GLI1 and GLI2 target genes in human chondrosarcoma." (PMID 30695055, 2019). "The GANT-61, as an inhibitor of GLI1, could inhibit chondrosarcoma tumor growth effectively by inhibiting the RNAP III signal pathway and tRNA-Gly-CCC synthesis in vivo." (PMID 37488121, 2023). "However, the gene coding for osteopontin (SSP), which has been shown to be transcriptionally activated by GLI1, was upregulated in four chordomas and one chondrosarcoma." (PMID 24452533, 2014). "In our early study, we have shown that GLI1 inhibition could significantly inhibit the growth and development of chondrosarcoma in vitro, but more work still needs to be carried out to verify the effect of GLI1 inhibition and fully elucidate GLI1 functions in vivo." (PMID 37488121, 2023). "The GLI1 transcription factor mediated RNAP III transcription signal pathway and tRFs synthesis has crucial roles in regulating chondrosarcoma proliferation, cell cycle, and cell death." (PMID 37488121, 2023). "Taking all the results together, the Hedgehog-GLI1 signal mediated the RNAP III signal pathway and tRNA synthesis to regulate the cell cycle and death receptor binding in chondrosarcoma." (PMID 37488121, 2023). "In this study we identified unique and overlapping GLI1 and GLI2 transcriptional targets in neoplastic chondrocytes taken from primary human chondrosarcoma which is known to exhibit activated Hh signaling." (PMID 30695055, 2019). "Identifying transcriptional targets of GLI1 and GLI2 in chondrosarcoma can provide mechanistic insight into the role of Hh signaling in tumor pathogenesis." (PMID 30695055, 2019).
chondrosarcoma (continued). "Then, Using qRT-PCR, we measured the expression of IHH, PTCH1, SMO, and GLI1 and found that their levels were significantly lower in normal articular cartilage compared to any other chondrosarcomas, particularly in dedifferentiated chondrosarcoma." (PMID 37488121, 2023). "We assessed the protein levels of GLI1 and GLI2 and found consistent results with the mRNA levels, suggesting that GANT-61 primarily reduces GLI1 expression rather than GLI2 in chondrosarcoma." (PMID 37488121, 2023). "Expression of PTCH1, SMO, and GLI1 proteins was detected in chondrosarcoma patient tissues and three chondrosarcoma cell lines (HC-a, SW1353, and JJ012), but not in normal articular cartilage tissues." (PMID 30081498, 2018). "Of note, data from this study indicated that activation of Hh signaling in chondrosarcoma cancer cells is type I noncanonical Hh signaling (GLI1-dependent and SMO-independent) since the Hh pathway activity can be diminished by GLI1 knockdown, but not by cyclopamine treatment." (PMID 30081498, 2018). "Interestingly, the gene coding for osteopontin (SSP), which has been shown to be transcriptionally activated by GLI1, was upregulated in four out of six chordomas and in one out of three chondrosarcomas in the cDNA microarray analysis (data not shown)." (PMID 24452533, 2014).
mesothelioma (9 papers, 2014 to 2025). A usually malignant and aggressive neoplasm of the mesothelium which is often associated with exposure to asbestos. "SMO and GLI1 in mesothelioma tissues detected high concordance between the diagnostic results of mesothelioma biopsy specimens and plasma cavity effusion specimens." (PMID 37139482, 2023). "Cox analysis showed that SMO and GLI1 gene expression levels, site of tumorigenesis, patient gender, and history of asbestos exposure were risk factors for survival time in mesothelioma patients (P < 0.05)." (PMID 37139482, 2023). "The increased Cul4A expression is associated with Gli1 expression in both mesothelioma tumours and in mesothelioma cells, and inhibiting Cul4A expression by siRNA decreased Gli1 expression in mesothelioma cells." (PMID 26218750, 2015). "We next analysed the association of Cul4A and Gli1 protein expression in 71 mesothelioma tumours (excluding two missing samples) and seven mesothelioma cell lines." (PMID 26218750, 2015). "Our analysis of mesothelioma cell lines showed that Cul4A and Gli1 expression is associated, which is similar to our observation in mesothelioma tumours." (PMID 26218750, 2015). "To further our understanding on the association of Cul4A and Gli1 expression in mesothelioma cells, we analysed mTOR expression after Cul4A knockdown by siRNA and mTOR expression was decreased." (PMID 26218750, 2015). "The increased Cul4A copy number and its association with Gli1 regulation in mesothelioma cells highlight Cul4A as a possible new therapeutic target for mesothelioma tumours." (PMID 26218750, 2015). "Cul4A expression also associated with Gli1 expression in mesothelioma tumours and in human mesothelioma cells, and inhibiting Cul4A expression by siRNA decreased Gli1 expression in mesothelioma cells." (PMID 26218750, 2015). "Statistical analysis revealed a significant association of Cul4A and Gli1 expression in these mesothelioma samples (P < 0.05, chi-square test)." (PMID 26218750, 2015). "Further study is needed to evaluate this hypothesis and understand the mechanism that underlies the increase in Gli1 expression when Cul4A is overexpressed in human mesothelioma." (PMID 26218750, 2015). "SMO and GLI1 gene expression levels, tumor site, patient's gender, and history of asbestos exposure were all risk factors for survival time in mesothelioma patients (P < 0.05), and the findings were consistent with greater significance for the prognostic value of mesothelioma." (PMID 37139482, 2023). "Our analysis also showed that immune cell infiltration mechanisms were associated with SMO and GLI1 expression, and that CD4+ T cells, neutrophils, and macrophages have an important impact on mesothelioma development and prognosis." (PMID 37139482, 2023). "SMO and GLI1 gene expression levels were negatively correlated with good prognosis in mesothelioma patients (P < 0.05)." (PMID 37139482, 2023). "The results of Spearman's correlation analysis in 130 patients with malignant mesothelioma showed a positive correlation between SMO protein and GLI1 protein expression in mesothelioma (R = 0.673) with statistically significant differences (P = 0.000)." (PMID 37139482, 2023). "The expression levels of SMO and GLI1 protein were correlated with the age, site, and asbestos exposure history of patients with mesothelioma." (PMID 37139482, 2023). "SMO and GLI1 genes were correlated with gender, age, tumor site, history of asbestos exposure, and staging of mesothelioma patients." (PMID 37139482, 2023). "SMO and protein expression of GLI1 genes had a significant effect on the survival prognosis time of patients with mesothelioma." (PMID 37139482, 2023). "The Cox proportional risk model showed that gender, history of asbestos exposure, site of occurrence, SMO, and GLI1 were independent prognostic factors for mesothelioma." (PMID 37139482, 2023).
mesothelioma (continued). "The expression levels of SMO and GLI1 protein and mRNA in mesothelioma tissues were higher than those in benign mesothelioma tissues." (PMID 37139482, 2023). "SMO and GLI1 gene expressions in mesothelioma were negatively correlated with age, site of occurrence, and history of asbestos exposure." (PMID 37139482, 2023). "Suppressing Hedgehog signalling reduced cell viability in MPM cells, and treatment with vismodegib in a rat model of mesothelioma reduced the expression of target genes such as GLI1, HHIP and PTCH1." (PMID 36138075, 2022). "CK2α activity is sufficient and necessary (CK2α-siRNA, CX-4945) to activate a Gli1 reporter in mesothelioma cell lines." (PMID 28134850, 2017). "CK2 plays a role in the control of Hedgehog (Hh)/Gli1 signaling, a pathway that is aberrantly upregulated in mesothelioma." (PMID 28134850, 2017). "Among 28 mesothelioma samples with strong Cul4A expression, 42.9% showed moderate Gli1 expression and 14.3% showed strong Gli1 expression." (PMID 26218750, 2015). "Inhibition of Gli1 by siRNA or small molecular inhibitors was shown to suppress mesothelioma cell growth in vitro and in a xenograft model." (PMID 26218750, 2015). "Next, we used Cul4A siRNA to inhibit Cul4A expression and analysed Gli1 protein expression in mesothelioma MS-1, 211H and H28 cells using western blotting." (PMID 26218750, 2015). "In mesothelioma cell lines, inhibiting Cul4A by siRNA decreased Gli1 expression, suggesting that Gli1 expression is, at least in part, regulated by Cul4A in mesothelioma cells." (PMID 26218750, 2015). "Taken together, these studies suggested that Gli1 expression is important to the survival of mesothelioma cells." (PMID 26218750, 2015). "Among the six mesothelioma cell lines that had moderate to strong Cul4A expression, four cell lines showed moderate to strong Gli1 expression." (PMID 26218750, 2015). "When Gli1 mRNA expression in the cell lysates was analysed using qRT-PCR, all the mesothelioma cell lines showed decreased Gli1 expression levels after Cul4A knockdown (P < 0.05, t-test)." (PMID 26218750, 2015). "Moderate staining (++) of Cul4A and Gli1 protein expression was detected in mesothelioma H2052 cells, and minimal staining (+) of Cul4A and Gli1 protein expression was detected in mesothelial LP-9 cells." (PMID 26218750, 2015). "Quantitative analysis of western blotting images showed that both Gli1 and mTOR protein levels were decreased after Cul4A knockdown in the mesothelioma cells." (PMID 26218750, 2015). "Among 30 mesothelioma samples with moderate Cul4A expression, 33.3% showed weak Gli1 expression and 10.0% showed moderate or strong Gli1 expression." (PMID 26218750, 2015). "In mesothelioma tumours, Cul4A and Gli1 expression were both increased compared to that in the normal pleural tissues." (PMID 26218750, 2015). "Because Gli1 expression was suggested to be critical to mesothelioma cell survival, we compared the protein expression of Cul4A and Gli1 in mesothelioma tumours and in mesothelioma cells." (PMID 26218750, 2015). "In this study, knocking-down Cul4A expression by using siRNA showed that Gli1 mRNA level and Gli1 protein level were both decreased in the treated mesothelioma cells, suggesting that inhibiting Cul4A decreased Gli1 expression." (PMID 26218750, 2015). "Because Gli1 is highly expressed in human mesothelioma cells, we compared Cul4A and Gli1 expression in mesothelioma tumours and found their expression associated (P < 0.05, chi-square)." (PMID 26218750, 2015). "This is consistent with findings from the recent study that first reported the role of aberrant Hh/Gli1 signaling in human mesothelioma." (PMID 25422081, 2014). "We then investigated their expression at the protein level, and found that all the 7 mesothelioma cell lines tested showed positive staining in CK2α and Gli1 immunohistochemistry." (PMID 25422081, 2014).
mesothelioma (continued). "In summary, we report that CK2 is over-expressed and positively regulates Hh/Gli1 signaling in mesothelioma." (PMID 25422081, 2014). "To analyze the relationship between CK2α and Gli1 in mesothelioma, we performed a Pearson product correlation test on CK2α and Gli1 staining in the 75 primary samples and the 7 cell lines." (PMID 25422081, 2014). "We therefore sought to detect CK2α and Gli1 expression in primary mesothelioma tissues and cell lines, and to analyze their relationship." (PMID 25422081, 2014). "First, by using the immunohistochemistry (IHC) staining, we detected the protein level of CK2α and Gli1 in 75 primary mesothelioma samples and 7 cell lines (H28, H290, 211H, H2452, MS-1, H226 and REN) of the tissue microarray sections." (PMID 25422081, 2014). "Third, in experimental studies of mesothelioma cell lines, CK2α inhibition by siRNA or small-molecular inhibitor resulted in down-regulation of Gli1 expression and transcriptional activity." (PMID 25422081, 2014). "Our study also suggests that CK2 is an additional target for the inhibition of Hh/Gli1 signaling in mesothelioma." (PMID 25422081, 2014). "Our study also demonstrates that Gli1 is over-expressed in mesothelioma, indicating the presence of an active Hh pathway." (PMID 25422081, 2014). "Quantitative RT-PCR was used to examine the mRNA level of CK2α and Gli1 in 44 primary mesothelioma samples and 8 mesothelioma cell lines (H28, H290, H2052, 211H, H2452, MS-1, H226 and H513)." (PMID 25422081, 2014). "Protein and mRNA levels of CK2α and Gli1 were tested by quantitative RT-PCR and immunohistochemistry staining in mesothelioma samples and cell lines." (PMID 25422081, 2014). "Correlation analysis by Pearson test for CK2α and Gli1 expression in the 75 mesothelioma tumors and the 7 mesothelioma cell lines showed that the two protein expression was significantly correlated (n = 82, r = 0.554, P < 0.01)." (PMID 25422081, 2014). "In the primary mesothelioma samples, the overall positive ratios of CK2α and Gli1 were both 93.3% (70/75)." (PMID 25422081, 2014). "△CtCa < △CtN indicated that the expression of SMO and GLI1 in mesothelioma tissues was higher than that in benign mesothelioma tissues; △CtCa > △CtN indicated that the expression in mesothelioma tissues was lower than that in benign mesothelioma tissues, and P < 0.05 was statistically significant." (PMID 37139482, 2023). "Interestingly, the higher the level of GLI1 expression, the shorter the survival time and the worse the prognosis of patients with mesothelioma, respectively." (PMID 37139482, 2023). "Human mesothelioma samples show a positive correlation between GLI1 and CK2α expression, and CK2α genetic silencing or pharmacological inhibition with the small-molecule CK2α inhibitor CX-4945 reduces the expression and transcriptional activity of GLI1." (PMID 30934935, 2019). "Thus, CK2α upregulation in mesothelioma correlates with upregulation of the transcript and protein for Gli1, the transcription factor of Hh signaling." (PMID 28134850, 2017). "In addition, we analysed Cul4A and Gli1 protein expression in mesothelial LP-9 and mesothelioma H2052 cells using ICC." (PMID 26218750, 2015). "Furthermore, by revealing the Cul4A-mediated Gli1 expression in mesothelioma, our study provides a rationale for developing therapeutic agents targeting Cul4A in mesothelioma tumours." (PMID 26218750, 2015). "Our results suggest a linkage between Cul4A and Gli1 expression in human mesothelioma." (PMID 26218750, 2015). "In addition, we compared Cul4A and Gli1 expression in seven human mesothelioma cell lines, including H2452, using IHC." (PMID 26218750, 2015). "Furthermore, we analysed mammalian target of rapamycin (mTOR) and Gli1 expression after Cul4A inhibition, and a potential linkage between Cul4A, mTOR and Gli1 expression in mesothelioma cells was suggested in this study." (PMID 26218750, 2015).